CDK4 (cyclin dependent kinase 4)
Diseases named in the same sentence as CDK4 in open-access papers (continued):
Sharing a sentence is not in itself a finding about the gene and the disease.
tumor (continued). "Beyond PD-L1 expression, CDK4/6 inhibitors can reshape the tumour immune microenvironment." (PMID 40563591, 2025). "Results highlight how the tumor microenvironment impacts CDK4/6 inhibitor response." (PMID 40032842, 2025). "Therefore, NEK6 regulates CDK2 and Bcl-2 through YBX1, which synergizes with CDK4/6 inhibitors to inhibit tumor growth." (PMID 41560755, 2025). "At the beginning of the systemic therapy after tumor progression during ET plus CDK4/6i treatment, patient age, the number of metastatic sites, the presence of visceral involvement, and the type of treatment (ET vs CT based) were similarly distributed in BRCA1/2 mutated vs wild-type groups." (PMID 39982725, 2025). "For example, ER-negative patients with low cytoplasmic NUB1 (mean IPS = 1.1% vs. 60.0%) in high-cytoplasmic NUB1 tumours may benefit from alternative regimens, such as CDK4/6 inhibitors, to bypass defective cell cycle checkpoints." (PMID 40564026, 2025). "Notably, both RPA1 and CDK4 mRNA levels were elevated in tumor tissues relative to adjacent normal tissues." (PMID 40593477, 2025). "We next investigated whether YAP1 target genes are involved in tumor‐promoting function of CDK4/6 in CRC." (PMID 39968498, 2025). "Overall, these findings suggest that GPER-mediated signalling within the TME may contribute to the reduced effectiveness of CDK4/6 inhibitors, underscoring the need to consider stromal-tumour interactions to overcome therapeutic resistance." (PMID 41388212, 2025). "However, it has been observed that tumor growth resumes, and the efficacy of CDK4/6 inhibitors diminishes upon treatment discontinuation." (PMID 40005476, 2025). "As previous reports showed that a combination of MEK and CDK4/6 inhibitors stimulated the accumulation of CD-8 + T-cells, immunological changes from combination therapy may differ between tumor types." (PMID 41428766, 2025). "Additionally, our study elucidated the diverse expression patterns within tumor cell subpopulations, offering insights into the heterogeneity of response to CDK4/6 inhibitors." (PMID 40303916, 2025). "Modulation of the tumor microenvironment, where immune cells are prominent components, arises as a feature of CDK4/6 inhibition and could be harnessed in therapeutic combinations." (PMID 40699853, 2025). "Hence, the potential involvements of other substrates of CDK4/6 besides YAP1 in tumor progression of HCC need to be further investigated." (PMID 40307228, 2025). "Additional targeted signals were noted for CDK4/6 and mTOR pathways: palbociclib limited proliferation and induced apoptosis via oxidative stress in CC models, and in combination with SHetA2 suppressed phospho-Rb and tumor growth in SiHa xenografts." (PMID 41303721, 2025). "However, a PROTAC-induced increase of mdm2 both in CDK4/6i sensitive and resistant MCF-7 cell is associated with a strong anti-tumor effect." (PMID 40452017, 2025). "Similar needs exist in patients with high-risk ER+/HER2− tumours, who are currently offered extended adjuvant endocrine therapy plus CDK4/6 inhibitors, with no possibility of de-escalation in patients with favourable prognosis based on their response to NACT." (PMID 40980814, 2025). "The primary end point was PFS in the clinical practice setting, defined as the time between the initiation of the first systemic treatment on tumor progression to ET plus CDK4/6i treatment and the detection of disease progression or patient death from any cause." (PMID 39982725, 2025). "Together, these findings substantiate the “dual role” of CDK4/6is in tumor immunity." (PMID 41463246, 2025). "In addition to tumor types that have been previously reported to have CDK4/6 as a potential therapeutic target, some other tumor types also displayed signs of CDK4/6 activation." (PMID 41035678, 2025).
tumor (continued). "While these molecular signatures distinguish tumour aggressiveness, only age and certain cell cycle genes (CDK4, CDKN1B) achieved independent prognostic significance in multivariate models, underscoring the need for further validation of molecular risk markers." (PMID 41007296, 2025). "Consequently, in addition to inhibiting tumor cell proliferation, CDK4/6is have also been found to affect tumor cells and the tumor microenvironment through mechanisms that are in early stages of clarification." (PMID 41463246, 2025). "This review presents a comprehensive analysis of the role of CDK4/6is in tumor immunity." (PMID 41463246, 2025). "The goal of the present investigation was to evaluate a highly sensitive tumor-informed ctDNA assay, with a test limit of detection (LoD95) of 0.001% variant allele frequency (VAF), in HR+/HER2− MBC patients receiving standard of care ET and CDK4/6i." (PMID 40683861, 2025). "While this dual blockade effectively suppresses tumor growth, acquired resistance inevitably arises, prompting exploration of post-progression strategies such as switching CDK4/6 inhibitors (e.g., palbociclib → ribociclib) or altering endocrine partners (e.g., fulvestrant → exemestane)." (PMID 40421216, 2025). "The CDK4/6-mediated phosphorylation is essential for the normal cell division process, and its hyperactivation results in excessive Rb protein phosphorylation, impairing its tumor-suppressor abilities and contributing to uncontrolled proliferation." (PMID 40149342, 2025). "By analyzing single-cell RNA-sequencing data from serial biopsies of patient tumors, we elucidated compensatory growth signaling pathways activated in ET + CDK4/6i-resistant cancer cells, along with the intercellular growth signal communications within the tumor microenvironment." (PMID 40341770, 2025). "Therefore, the cyclin D-CDK4/6-Rb signaling pathway plays a critical role in cell cycle regulation, and inhibition of CDK4/6 has become an effective strategy for tumor treatment." (PMID 41463246, 2025). "Our scRNA-seq analysis identified a panel of biomarkers from BL tumor cells that we hypothesized were predictive of CDK4/6i treatment response." (PMID 39955556, 2025). "For cases with conflicting prognostic signals, relative contraindications or drug interactions, and/or uncertainty around the choice of CDK4/6 inhibitor, we recommend collaborative decision-making through multidisciplinary team reviews, with tumour boards reserved for complex cases." (PMID 40862813, 2025). "In addition to the immune surveillance-promoting effects of CDK4/6 inhibitors on immune cells within the TME, these agents are also associated with immunological changes in tumour cells." (PMID 41388212, 2025). "This study comprehensively summarizes the molecular mechanisms by which CDK4/6 inhibitors activate or suppress anti-tumor immunity and reveals the dual effects of CDK4/6 inhibitors on influencing interferon signaling, mediating senescence, and altering certain immune cells." (PMID 41463246, 2025). "CDK4/6 inhibitors work by slowing down tumor progression and enhancing tumor responses in the bone." (PMID 40424680, 2025). "Additionally, CDK4/6 inhibitors activate the expression of endogenous retroviral elements in tumor cells, stimulate the production of type III interferons, and further boost antigen presentation in tumors." (PMID 40836337, 2025). "CDK4/6 inhibitor (CDK4/6i) induces antitumor immune phenotypes by targeting both tumor and immune cells, enhancing immune checkpoint blockade (ICB), but optimal combination modalities and the corresponding cellular mechanisms remain unclear." (PMID 40936164, 2025). "In addition, multiple MyD88-related pathways were enriched, supporting prior evidence that CDK4/6 inhibitors can reprogram the tumor microenvironment by modulating the IL-33–MyD88 axis, therefore inhibiting suppressive immune cells." (PMID 40856900, 2025).
tumor (continued). "Additionally, it is also worth noting that the severe adverse events caused by the combination of CDK4/6is and ICI are currently the main obstacle to the application of CDK4/6is in anti-tumor immunotherapy." (PMID 41463246, 2025). "Since MAPK pathway activation is upstream of cell proliferation, we hypothesized that MEK inhibitors may increase the anti-tumor effects of CDK4/6 inhibitors." (PMID 41428766, 2025). "Alterations in USP1 activity could therefore compromise the efficacy of palbociclib by enabling tumor cells to evade CDK4/6-mediated cell cycle arrest or by improving DNA repair capacity." (PMID 40940964, 2025). "Blocking CDK4/6 with inhibitors increases PD-L1 levels, enhancing immune suppression, which suggest that combining CDK4/6 inhibitors with PD-1/PD-L1 immunotherapies could disrupt tumor immune evasion and improve patient outcomes." (PMID 40034825, 2025). "For somatic copy number alterations, cases with high PLK3 expression not only demonstrated significant amplification peaks for PIK3C2B, PDGFRA, EGFR, and CDK4, which are defined as oncogenic drivers, but they also showed deletion peaks for tumor-suppressor genes, such as CDKN2A and CDKN2C." (PMID 39866232, 2025). "In parallel, CDK4/6 inhibition hampers tumour progression, therefore promoting the accumulation and maturation of NK cells, a further critical component of the tumour immunosurveillance from which may arise the natural killer/T-cell lymphoma (NKTL)." (PMID 41388212, 2025). "Notably, next-generation sequencing analysis of tumor tissue, blood, and cerebrospinal fluid (CSF) uniquely revealed an increased copy number of cyclin-dependent kinase 4 specifically in the CSF." (PMID 40696621, 2025). "Notably, CDK4/6is, combined with anti-PD-1 therapy, enhanced tumor sensitivity and significantly improved the overall survival (OS) rates in mouse tumor models." (PMID 40244377, 2025). "Furthermore, the impacts of circACTN4 on the MYC expression, CCNE1, and CDK4 were detected via immunohistochemistry (IHC) in transplanted tumor tissues." (PMID 40612865, 2025). "Considering that treatment with radiotherapy or a CDK4/6 inhibitor can enhance anti-tumor immunity in vitro, we analyzed the impact of new neoadjuvant therapeutic regimen on alternation in biomarker expression in the numbers of TILs before and after the treatment." (PMID 40719174, 2025). "In addition to a direct effect on cancer cell survival, CDK4/6i have been shown to promote anti-tumor immune responses." (PMID 40696167, 2025). "Preclinical studies and early-phase clinical trials suggest that CDK4/6 inhibitors may enhance anti-tumor immunity by promoting T-cell activation and reducing Tregs in the TME." (PMID 40566067, 2025). "The radiosensitizing effect of CDK4/6 inhibitor, observed in preclinical studies, is attributed to their ability to inhibit DNA damage repair induced by RT and therefore increasing tumor cytotoxicity." (PMID 40649034, 2025). "ET plus CDK4/6i is the current standard frontline for most patients except for imminent organ failure due to malignant disease, including fit elderly patients and high tumor burden." (PMID 40361341, 2025). "This supports the notion that prolonged treatment with CDK4/6 inhibitors may exert greater tumor-suppressive effects compared to short-term assays." (PMID 40642276, 2025). "Multiple PDX and cell-line xenograft studies validate the synergistic antitumor activity of combined PI3Kα and CDK4/6 inhibition; some models showed durable regressions while others exhibited tumor stasis, highlighting dependency on tumor genotype and treatment scheduling." (PMID 41280894, 2025). "Despite the improvements achieved, resistance to ET and CDK4/6is, as well as tumor progression, may be an occurrence following extended periods of disease control in which disease-related symptoms are observed to be non-existent or minimal." (PMID 40558242, 2025).
tumor (continued). "Besides cardinal ramifications for the cell cycle inhibition, CDK4/6 inhibitors have anti-tumor immunity-promoting effects which are derived from the inhibition of E2F1." (PMID 40699853, 2025). "We also found that CDK4/6 inhibition by abemaciclib dramatically reduced YAP1 expressions while concurrently upregulating cleaved‐poly(ADP‐ribose) polymerase‐1 (PARP1) levels in tumor samples from saline‐treated mice." (PMID 39968498, 2025). "In this cohort study, the duration of tumor control achieved with CDK4/6i-based therapy and the presence of visceral metastases emerged as key factors that may affect treatment decision." (PMID 39982725, 2025). "Recently, CDK4/6 inhibition (CDK4/6i) is demonstrated to enhance antitumor immunity, as evidenced by increased tumor infiltration of CD8+ T cells; however, the mechanism underlying this phenomenon remains unclear." (PMID 41082324, 2025). "By clearing these cells and preventing their escape from dormancy, this approach enhances the antitumor durability of CDK4/6is, reduces the residual disease burden, and fosters a tumor microenvironment less conducive to recurrence, thereby improving long-term outcomes in patients." (PMID 39865083, 2025). "Furthermore, amplification or overexpression of the MDM2 (Murine Double Minute 2) and CDK4 genes has been observed in OS, suggesting their involvement in tumor development." (PMID 40076599, 2025). "Mechanistically, CDK4/6 inhibitors induce tumor cell cycle arrest and apoptosis, while chemotherapy-induced DNA damage may sensitize tumors to cell cycle-targeted therapies." (PMID 40421216, 2025). "Preclinical studies have also suggested that CDK4/6 inhibitors may increase tumor cell immunogenicity and are being explored as candidates for combination therapy with immunotherapies." (PMID 39858514, 2025). "Taken together, our findings reveal the previously unrecognized tumor-promoting function of CDK4/6-DUB3 axis through stabilizing YAP1, providing preclinical evidence that targeting this axis may represent a promising therapeutic strategy for HCC." (PMID 40307228, 2025). "This study also provides a detailed summary of how CDK4/6is suppress anti-tumor immunity." (PMID 41463246, 2025). "We and others have observed anti-tumor efficacy of CDK4/6 inhibitors in EC preclinical models." (PMID 41560755, 2025). "The result implied that the combination of Exo-siTMEM45A and palbociclib significantly benefited tumor CDK4/6 inhibitor therapy and the delivery of siTMEM45A by engineered exosomes might significantly reduce the use of palbociclib." (PMID 39910045, 2025). "Furthermore, the complex mediates E2F-dependent transcriptional activation, enabling recognition of both CDK4 and CDK2 substrates, demonstrating dual functional properties associated with cell proliferation and tumor cell transformation." (PMID 41471692, 2025). "Screening novel small molecules against both VEGFR-2 and CDK4 offers a comprehensive approach to identify potential multi-targeted agents capable of simultaneously disrupting two fundamental and complementary pathways of tumor progression." (PMID 41471388, 2025). "Consequently, clinical evidence clarifying how CDK4/6is activate or suppress anti-tumor immunity remains limited." (PMID 41463246, 2025). "Moreover, the combination of ET and a CDK4/6i was compared with dual chemotherapy in patients with aggressive tumor characteristics, and the results showed similar efficacy with a better safety profile." (PMID 40361341, 2025). "Trilaciclib, a CDK4/6 inhibitor approved for the indication of reducing the risk of myelosuppression, has not been found to have anti-tumor effects in previous studies." (PMID 41463246, 2025). "Tumours with exceptionally high ER expression likely exhibit maximal dependence on the ER signalling pathway, rendering them particularly vulnerable to the combined ER pathway and CDK4/6 inhibition." (PMID 41440236, 2025).
tumor (continued). "Specifically, we revealed that the inhibition of NEK6 by genetic modification or ZINC05007751, a NEK6 selective inhibitor, could enhance the anti-tumor effects of palbociclib (a CDK4/6 inhibitor) in cell lines, patient-derived organoids and mouse models of EC." (PMID 41560755, 2025). "Furthermore, in vivo experiments with mice bearing human colon carcinoma xenografts proved that inhibition of CDK4/6 alone was sufficient to induce marked tumor regression." (PMID 39800748, 2025). "In addition, CDK4/6 inhibitors inhibit tumor growth through several mechanisms such as promoting tumor cell senescence and altering the immune environment of tumor cells." (PMID 40486867, 2025). "Based on these findings supporting the clinical importance of combination regimens, including CDK4/6 inhibitors and ICIs, ongoing clinical efforts aim to evaluate this therapeutic strategy in various tumours towards the identification of predictive biomarkers and patient selection." (PMID 41388212, 2025). "In addition, CDK4/6 inhibition decreases the number of myeloid cells, which are crucial for antigen presentation and immune response coordination within the tumor microenvironment." (PMID 39930131, 2025). "Additionally, CDK4/6is have been reported to influence the activation of effector T cells by acting on tumor cells." (PMID 41463246, 2025). "Interestingly CDK4/6 inhibitors were also reported to exhibit a positive impact within the tumor immune microenvironment by augmenting the antitumor immunity." (PMID 40856900, 2025). "Abemaciclib also inhibits CDK2/Cyclin A/E and CDK1/Cyclin B. In addition to cell cycle blockade, CDK4/6i can also induce a senescence-like state, promote epigenetic remodelling, autophagy, blockade of oncogenic signalling networks and promote tumor immunogenicity." (PMID 40764324, 2025). "As SMARCA4 inactivation is known to be synthetic lethal with CDK4, PP tumours with SMARCA4 mutations and high CDK4 activity may respond well to CDK4/6 inhibitors." (PMID 40849356, 2025). "Furthermore, numerous studies have revealed that CDK4/6 inhibitors are effective not only in the G1 phase but also in suppressing tumor growth during the S and G2 phases." (PMID 40486867, 2025). "Several preclinical and translational studies suggest that adding to ICIs a second agent, such as chemotherapy, CDK4/6i, or PARPi, may elicit an anti-tumor immune response, ultimately resulting in a synergistic effect." (PMID 40941037, 2025). "Our hypotesis that, by inhibiting angiogenesis, renin-angiotensin system inhibitors may reduce tumor growth and improve the effectiveness of cyclin-dependent kinase 4/6 inhibitors by cutting off the supply of nutrients and oxygen to the tumor." (PMID 41417371, 2025). "Non-HPV-related HNSCC is caused by the overactivation of the CDK4/6 and cyclin D1 regulatory complex, resulting in cell cycle progression and tumor growth, suggesting that CDK4/6 inhibition may be a rational therapeutic strategy in this case." (PMID 40864763, 2025). "Longer tumor control during ET plus CDK4/6i therapy may reflect a more indolent and endocrine-sensitive disease, which could imply a better response to subsequent treatments and longer disease control." (PMID 39982725, 2025). "The use of CyclinD1/CDK4 together with hTERT overexpression has been recognized as an established method to extend cellular life span, preserving the original nature of primary epithelial cells from a variety of tumor types." (PMID 40427213, 2025).